PDILT (protein disulfide isomerase like, testis expressed)
Description:
Probable redox-inactive chaperone involved in spermatogenesis.
Synonyms: PDIA7
Tractability: Antibody: UniProt predicts a signal peptide or a membrane-spanning region.
Gene: Protein-coding gene on chromosome 16 (20,359,175 to 20,404,737, reverse strand). Ensembl gene ENSG00000169340.
Subcellular location: Endoplasmic reticulum
Gene Ontology:
Molecular function: protein folding chaperone; protein disulfide isomerase activity
Biological process: protein folding
Cellular component: endoplasmic reticulum
Genetic constraint (gnomAD): Loss-of-function variants: 43 observed, 55.92 expected, observed/expected ratio (o/e) 0.77, 90% interval 0.6 to 0.99. The upper end of that interval is the gene's LOEUF score, 0.99, which puts it in group 4 of 6, group 1 being the genes least tolerant of losing a copy. Missense variants: 726 observed, 747.04 expected, observed/expected ratio (o/e) 0.97, 90% interval 0.91 to 1.03. Synonymous variants: 281 observed, 289.12 expected, observed/expected ratio (o/e) 0.97, 90% interval 0.88 to 1.07.
Homologues: Orthologues: chimpanzee PDILT (98% identical), macaque PDILT (93% identical), dog PDILT (79% identical), rabbit PDILT (79% identical), pig PDILT (74% identical), mouse Pdilt (71% identical), rat Pdilt (70% identical), guinea pig PDILT (69% identical), tropical clawed frog pdilt (39% identical), zebrafish zgc:136472 (27% identical), Caenorhabditis elegans pdi-2 (26% identical), Drosophila melanogaster Pdi (25% identical), and 7 more. Paralogues in human: P4HB (28% identical), PDIA2 (28% identical), PDIA4 (20% identical), PDIA3 (19% identical), TXNDC11 (15% identical), TXNDC5 (14% identical), PDIA5 (14% identical), ERP44 (14% identical), PDIA6 (13% identical), TMX3 (12% identical), ERP27 (12% identical), TMX4 (9% identical), and 1 more.
Diseases named in the same sentence as PDILT in open-access papers:
PDILT is named in the same sentence as 6 diseases in open-access papers, as found by Europe PMC text mining. Sharing a sentence is not in itself a finding about the gene and the disease. The quoted sentences say what the papers report.
Infertility (3 papers, 2016 to 2024). "The gonadal-specific expression of MAGEB2 and PDILT raises the questions whether these antigens may have a role in infertility in APS1." (PMID 26830021, 2016). "Moreover, two novel gonadal autoantigens, melanoma antigen family B 2 (MAGEB2) and protein disulfide isomerase-like testis (PDILT), have been identified that potentially could contribute to infertility in male and female patients with APECED." (PMID 27597936, 2016). "The identification of MAGEB2 and PDILT reveals the gonadal germ cells as major immune targets in APS1, and discloses yet another autoimmune component that potentially could contribute to infertility in male and female patients with APS1." (PMID 26830021, 2016).
Hypertension (2 papers, 2021 to 2022). The presence of chronic increased pressure in the systemic arterial system. "We also found a significant association at the PDILT/UMOD locus (lead SNP rs77924615), that colocalises with hypertension, cystatin C, creatine, and kidney and urinary calculus in the UKBB." (PMID 34128465, 2021).
Autoimmunity (1 paper, 2017). The occurrence of an immune reaction against the organism's own cells or tissues. "Our study is in contrast to previous report, which identified only two novel targets (PDILT and MAGE-B2), also detected by our screening here, and with a key observation that autoimmunity in APECED preferentially targets molecules with restricted tissue expression profiles." (PMID 28861084, 2017).
PDILT also shares sentences with these, for which no sentence is quoted: diabetes (1 paper); gastric cancer (1); kidney stone (1).